BCL2 (BCL2 apoptosis regulator)
Diseases named in the same sentence as BCL2 in open-access papers (continued):
Sharing a sentence is not in itself a finding about the gene and the disease.
tumor (continued). "For example, induction of BCL-2 oncoprotein expression by oestrogen contributes to suppression of apoptosis and BCL-2 and oestrogen receptor (ER) are frequently co-expressed in tumours." (PMID 10576663, 1999). "Immature tumour cells adjacent to thin fibrovascular stroma are proliferating, as evidenced by PCNA positivity, and often express Bcl-2." (PMID 9099968, 1997). "Anti-apoptotic BCL2 was upregulated in all tumor cells from nonresponsive lesions, especially in CD30- subsets." (PMID 41762706, 2026). "Using an in vitro co-culture system to assess CD8+ T cell killing of tumour cells, we identified compounds that inhibit Bcl-2 and Bcl-xl as agents that can induce tumour cell death without impacting the differentiation or function of anti-tumour T cells." (PMID 41495028, 2026). "Furthermore, in CT26 tumor-bearing mice, Alb-TAC#2 achieved extensive apoptosis through robust BRD4 degradation, leading to marked downregulation of c-Myc, Bcl-2, and PD-L1." (PMID 42094600, 2026). "In CRC, however, SLC46A1 downregulation induces intracellular folate deficiency, triggering locus-specific DNA hypomethylation at the FOS promoter, which activates oncogenic transcription of key downstream effectors (CCND1, BCL2, PLAU), driving tumor progression." (PMID 41620398, 2026). "It was found that it regulated cellular responses along with apoptotic mechanisms in cells without developing resistance in suppressing tumor growth by making changes on Atf2, Casp8, Bcl2 and Irf5 genes and proteins." (PMID 41656578, 2026). "Expression levels of Bax, Bcl‐2, and PARP were used as markers of tumor apoptosis." (PMID 41513589, 2026). "In tumor-bearing mice, PEG-HMS-DTX achieved superior tumor accumulation (peak at ∼12 h), pronounced tumor growth inhibition (>70%), minimal systemic toxicity, and elevated apoptosis characterized by increased cleaved caspase-3 and reduced PCNA/Bcl-2 expression." (PMID 41675220, 2026). "Venetoclax, a selective small‐molecule BCL‐2 inhibitor that binds directly to the BH3 domain of the BCL‐2 family protein, stimulates changes in mitochondrial outer membrane permeability and caspase activation to achieve rapid apoptosis of tumor cells." (PMID 40062510, 2025). "Moreover, IHC staining demonstrates that the expression of BCL‐2, c‐FLIP and XIAP in tumour tissues is also effectively inhibited by imipramine treatment." (PMID 40889216, 2025). "Furthermore, the present study found a strong correlation between the expression of target genes (IL10RB, INHBB, NEO1, PIK3R1, BCL2, ID4, and INHBA) and the infiltration of tumor-killing cells into the tumor immune microenvironment in HNC." (PMID 40647469, 2025). "In B-cell lymphoma models, combining Venetoclax with CD19 CAR-T cells significantly enhanced tumor cell apoptosis and improved CAR-T cell persistence, demonstrating its potential clinical application for patients harboring BCL-2-expressing leukemia and lymphoma." (PMID 41169368, 2025). "Moreover, anti-apoptotic BCL2 proteins promote hedgehog/Gli signaling by enhancing the turnover of a Gli antagonist, SUFU tumor suppressor to inhibit Gli-SUFU interaction, thus increasing the expression of Gli target genes such as BCL2." (PMID 41353440, 2025). "In LNCaP cells, where BCL-2 transcription did not change significantly, the strong induction of these tumor suppressor miRNAs likewise suggests decreased anti-apoptotic BCL-2 activity at the protein level." (PMID 41465187, 2025). "The tumor exhibits positivity for Vimentin, PR, and SMA, with negativity for PanCk, S100, Desmin, PSA, CK5/6, BCL2, MDM2, and Melan A. Additionally, the Ki-67 proliferation index is approximately 25 %, and CD34 highlights only the vascular walls without tumor cell positivity." (PMID 40686513, 2025).
tumor (continued). "Lastly, Lewis mouse transplant tumor experiments showed that SH inhibited tumor growth, reduced the protein expression of Ki-67, VEGFA and CD31 in transplanted tumor tissues, and the mRNA expression of MMP-2 and Bcl-2, while promoting the expression of Bax mRNA." (PMID 41444284, 2025). "Aberrant hyperactivation of the JAK2/STAT3 axis is frequently observed in TNBC and has been shown to transcriptionally upregulate anti-apoptotic genes such as Bcl-2 and Survivin, facilitate epithelial–mesenchymal transition (EMT), and promote tumor cell migration, invasion, and immune evasion." (PMID 40936705, 2025). "The threshold effect mirrors the findings reported by some groups who proposed that minor BCL-2+ subclones can eventually dominate in a conducive tumor microenvironment." (PMID 40699745, 2025). "The lack of significant differences in VEGF, BAX, and BCL2 expression indicates that dynamic culture conditions preserve the tumor phenotype while providing a more controlled and “biomimetic” in vitro environment." (PMID 41439917, 2025). "The top five genes with the highest degree values are AKT1, SRC, EGFR, BCL2, and CASP3, suggesting that FOA may exert its anti-tumor effects by acting on multiple targets." (PMID 41050420, 2025). "Immunohistochemically, tumor cells express TLE1, EMA, CK19, and some cases could express S-100, CD99, and Bcl-2." (PMID 40826697, 2025). "Targeted oncogenes such as EGFR, Bcl-2, and KRAS, which are frequently overexpressed in various cancers, have been successfully silenced using siRNA-based approaches, demonstrating enhanced tumor suppression and chemosensitization." (PMID 40573996, 2025). "Consistent with these in vitro findings, analysis of xenograft tumor tissues revealed a similar downregulation of COX2, iNOS, Vimentin, and Slug, together with an upregulation of Bax and suppression of Bcl2, further supporting the induction of mitochondria‐mediated apoptosis by FPHPE." (PMID 41200213, 2025). "While the initial tumor did not stain for BCL2 by immunohistochemistry, the recurrent tumor tissue taken to establish the cell line stained positive for BCL2 in 50 % of tumor cells." (PMID 39970625, 2025). "The results indicated that, in the tumor cells of either MCF-7 or A549 treated with VH-HT3, the expression of pro-apoptotic protein Bax increased, while the expression of anti-apoptotic protein Bcl-2 decreased significantly." (PMID 40508092, 2025). "Immunofluorescence staining demonstrated significant reductions in STAT3 and downstream proteins (VEGF, cyclin D1, c-Myc, BCL-2, and PD-L1) post-treatment, confirming D11-PROTAC’s ability to downregulate these proteins in tumor tissues, aligning with its cellular effects." (PMID 40118821, 2025). "The tumor was classified as CD20(+), BCL6(+), BCL2(+), and Ki-67(+, 60%)." (PMID 41261693, 2025). "A biopsy of the retroperitoneal tumor showed proliferation of small, atypical lymphoid cells with high nuclear-to-cytoplasm ratio, positive for CD10, CD19, CD79a, BCL-2, BCL-6, and c-MYC by immunohistochemistry." (PMID 41142614, 2025). "Therefore, we investigated Bcl-2 expression in CD68+CD86+ M1 macrophages in DLBCL samples (intra-T vs peri-T) and in DLBCL vs non-tumor control lymph node samples." (PMID 41415285, 2025).
tumor (continued). "Mechanistically, POLR2J4 knockdown reduced the expression of drug resistance genes (ABCB1, ABCC1, BCL2), decreased serum levels of IL-6 and TGF-β1, and downregulated TGF-β1 and PD-L1 in tumor tissues, highlighting its role in establishing an immunosuppressive, drug-resistant microenvironment." (PMID 40661083, 2025). "Immunohistochemically, the tumor cells were positive for ki-67, bcl-2, CD10, bcl-6, and CD38, but negative for bcl-2 and MUM-1." (PMID 39993110, 2025). "This may suggest that whereas BCL2/BCL-XL decreases in IBD, it is high in cancer; hence, elevated BCL2/BCL-XL may be required for tumor growth in cancer." (PMID 40534879, 2025). "Second, a T24 xenograft mouse model demonstrated that the (DOX + ISB) group exhibited greater tumor suppression than the DOX (p = 0.08) and ISB (p = 0.02) groups, with decreased Ki‐67 and Bcl‐2 expression and increased apoptosis (all p < 0.01) in an in vitro study." (PMID 41244330, 2025). "More precisely, mRNA and protein levels of BCL-2 and XIAP were reduced in the presence of SAFit, suggesting that, by counteracting NF-κB activation, SAFit is able to turn off the survival pathways of the tumor." (PMID 40180895, 2025). "However, miR-1290 counteracts the tumor-suppressive effects of CDR1 by modulating the expression of apoptosis-related factors, including Bcl-2, Bax, and caspase-3, and facilitating tumor spread." (PMID 39944625, 2025). "In addition, Rh inhibits tumor growth by activating apoptosis-related proteins, including caspase-3, BCL-2, and BAX, and by suppressing tumor angiogenesis." (PMID 41471822, 2025). "This tumor-suppressive effect involves inhibition of the NF-κB pathway, as evidenced by reduced nuclear localization of RelA and decreased expression of NF-κB target genes, including cIAP, XIAP, BCL2, and Survivin." (PMID 40562870, 2025). "Similarly, western blot analysis of tumor tissues confirmed that DT‐13 suppressed PCNA and Bcl‐2 expression." (PMID 41476787, 2025). "Additionally, mIDH1 AML exhibits increased dependence on the anti-apoptotic protein BCL-2, and the BCL-2 inhibitor venetoclax induces apoptosis and tumor regression in both in vitro and in vivo models." (PMID 40931345, 2025). "Although studies on Bcl-2 in HCC are sparse, some evidence suggests that Bcl-2 downregulation may be related to tumor growth and poor prognosis." (PMID 40740599, 2025). "This pathway is known to upregulate the expression of oncogenes such as c‐Myc and Bcl‐2 while enhancing the production of inflammatory cytokines like interleukin‐6 (IL‐6) and tumor necrosis factor‐alpha (TNF‐α), thereby creating a tumor‐promoting microenvironment." (PMID 40387523, 2025). "The results of network pharmacology and molecular docking analyses suggested that SSA may interact with BCL2, ESR1, HIF1A, and STAT3 as well as PI3K/AKT signalling pathways and inhibit tumour growth by promoting apoptosis." (PMID 39995416, 2025). "Therefore, NEK6 regulates CDK2 and Bcl-2 through YBX1, which synergizes with CDK4/6 inhibitors to inhibit tumor growth." (PMID 41560755, 2025). "Moreover, the use of next-generation inhibitors of anti-apoptotic proteins BCL-2, BCL-XL, and MCL-1 induces apoptosis in in vitro and in vivo tumor models." (PMID 38891056, 2024). "BCL-2 also shows promise in clinical outcomes of CAR-T treatment and resistance to small molecules promoting tumor apoptosis, undergoing intense preclinical and clinical research in hematologic malignancies, mimicking the action of the BH3-only proteins, including venetoclax." (PMID 38891056, 2024). "Other studies have found that these factors can also affect the prognosis of TNBC, including tumor-infiltrating lymphocytes (TILs), CD103 iTIL density, positive prolactin receptor, adipophilin, erythropoietin receptor and increased Bcl-2 expression." (PMID 38827797, 2024).
tumor (continued). "Obatoclax is an early pan-BCL-2 inhibitor that can antagonize BCL-2, BCL-xl, BCL-w, and MCL-1 and promote the activation of Bax/Bak and subsequent caspase-3 activation, ultimately leading to the apoptosis of tumor cells." (PMID 39060763, 2024). "Additionally, we found that treatment of MCC cell lines with various small-molecule inhibitors, such as Bcl-2 inhibitors, epigenetic modifiers, BET degraders, and ADCs, has facilitated apoptosis and tumor volume reduction in MCC mouse xenograft models." (PMID 39456853, 2024). "Normal cells are not significantly affected by Bcl-2 protein inhibitors because tumour cells express the protein at far higher levels than normal cells do." (PMID 38223131, 2024). "BCL-2 homology domain (BH3) profiling is a functional assay that interrogates tumour intrinsic apoptotic pathway function without the need to establish an ex vivo cell culture." (PMID 39572533, 2024). "Similarly, CM-272 showed potent antitumor effects when combined with proapoptotic agents (Bcl-2 inhibitor venetoclax, BCL-XL inhibitor A1331852, MCL-1 inhibitor S63845) in multiple tumor types." (PMID 39488528, 2024). "However, recent immunohistochemical studies have revealed that tumor cells in SFTs lack mesothelial characteristics but express CD34 and Bcl-2, suggesting that the tumor originates from mesenchymal tissues." (PMID 39206171, 2024). "Western blotting results showed that the protein levels of cell cycle-related proteins cyclin B1, cyclin D, and anti-apoptotic protein Bcl-2 had decreased, while the apoptosis-related protein Bak had increased both in NSCLC cells and in A549-xenografted tumor tissues." (PMID 38287075, 2024). "First, we confirmed that loading Bcl2 siRNA did not affect the ability of αCD7/EVs/CytC to target Molt‐4 tumours." (PMID 39676736, 2024). "The proliferative activity of tumor tissue remained unaffected, and there was no suppression of apoptosis, as evidenced by the absence of BCL2 oncogene expression." (PMID 39275182, 2024). "Ginsenoside Rg3 in combination with TAE has been shown to significantly decrease CD31, VEGF expression, and levels of the anti-apoptotic Bcl-2 at both mRNA and protein levels, while significantly increasing pro-apoptotic gene caspase-3 and Bax expression in VX2 rabbit tumor models." (PMID 39204162, 2024). "By diminishing the level of cyclin B1 and regulating the phosphorylation of protein kinase Chk1 and p21, the level of Bcl-2 was significantly reduced, and the BAX, cytoplasmic Cytochrome-C (Cyt c), Caspase-9 and Caspase-3 levels were increased to produce an anti-tumor effect." (PMID 38675663, 2024). "Having identified robust fixation and permeabilization conditions that did not compromise RNA quality, the next step was to verify BCL2 overexpression as a unique biomarker to distinguish tumor B cells within a pool of normal B cells." (PMID 38280422, 2024). "SCRIPro could accurately predicts well-known master regulators including SPI1, IRF1, FLI1, and STAT2 for mono/macrophages, GATA3, RUNX3, SMARCA4, JUND, and MYB for T-cells, PAX5, BCL2, and IRF4 for B and tumor B-cells." (PMID 39024032, 2024). "In models of a VX2 liver xenograft tumor, the combination of rapamycin with TACE has also been demonstrated to exhibit anti-tumor neovascularization activity and to inhibit the expression levels of iNOS, HIF-1α, VEGF, Bcl-2, and Bax." (PMID 39204162, 2024). "Tumor cells regained sensitivity to ABT-737 or Venetoclax as Mcl-1 gene was knocked out in leukemia cells, which suggested Mcl-1 was the primary reason of resistance to anti-Bcl-2 compounds." (PMID 39372954, 2024).
tumor (continued). "In a phase 1 clinical trial of a Bcl-2–targeting ASO (G3139), a decline in Bcl-2 expression was observed, but no significant anti-tumor response was noted." (PMID 39272802, 2024). "In addition, IHC staining revealed decreases in the expression of the cell proliferation marker Ki67 and the antiapoptotic protein Bcl-2 in MAGOH-knockdown tumors, indicating that MAGOH knockdown inhibited tumor growth." (PMID 38268030, 2024). "Through cell function and mechanism studies, it was found that compounds 7a and 7j downregulated the expression of Bcl-2, Caspase9, and MMP9 proteins, upregulated the expression of Cleaved-Caspase3 and Cleaved-PARP proteins, inhibited tumor cell proliferation and migration, promoted cell apoptosis." (PMID 38649732, 2024). "Bcl-2 inhibitors have been used in various hematologic malignancies, mainly in combination with other chemotherapies, with promising results for patients’ survival, which led to their approval by the FDA and EMA for these types of neoplasms." (PMID 38610812, 2024). "In melittin-treated tumor cells, we observed a significant increase in the expression levels of Bax, Cytochrome C, AIF, Endo G, and Smac/Diablo, accompanied by a notable decrease in Bcl-2 expression." (PMID 39519238, 2024). "It targets nearly 30 genes, including tumor suppressors such as CDK2AP1, Pdcd4, and BCL2." (PMID 38790924, 2024). "According to the fifth edition of the WHO Classification of Tumours of Haematopoietic and Lymphoid Tissues, 26 patients (93%) were classified as DLBCL-NOS, and 2 patients (7%) were classified as HGBCL with MYC and BCL2 rearrangements." (PMID 38542066, 2024). "These proteins are essential for apoptosis (Bcl-xL, Bcl-2, c-IAP1, Mcl-1, c-IAP2, XIAP), the cell cycle (cdc-25, cyclins D1, B1 and A1), anti-tumor (ADAM10, HSP70, p21, Myc, RNA polymerase, p27) and inflammatory activities and immuno-regulation (TNF-a, IL-1, IL-4, IFN-a, IL-6, IL-2, CD80, CD40)." (PMID 38293343, 2024). "In addition, W. coagulans MZY531 regulates the Bax/Bcl-2/caspase-3 and JAK2/STAT3 apoptosis pathways and PI3K/AKT/mTOR pathways, as well as TGF-β/SMAD4 autophagy pathways, thereby attenuating tumor growth." (PMID 39459634, 2024). "Furthermore, SIVA-1 overexpression with DDP treatment synergistically inhibited tumor growth in vivo by increasing PCBP1 and decreasing Bcl-2 and Bcl-xL expression." (PMID 38947376, 2024). "Furthermore, the result of the transplanted tumor model indicated that TMG substantially enhanced the activities of Bax and caspase-3, reduced the activity of Bcl-2, and suppressed the expression of Raf/MEK/ERK protein levels." (PMID 39845805, 2024). "An increase in pro-apoptotic BCL-2 proteins after a DNMT1 blockade could restore cell death, which tumor cells would otherwise avoid." (PMID 39595939, 2024). "In immunohistochemistry, tumor cells diffusely expressed CD45, CD56, CD4, BCL2 TdT and CD43." (PMID 39210931, 2024). "Glabridin increases intracellular and mitochondrial ROS production, downregulates Akt and ERK1/2 phosphorylation to inhibit tumor cell proliferation, and upregulates p38 and JNK phosphorylation, increasing Bax, activating caspase-3 and PARP cleavage, and decreasing Bcl-2 to enhance apoptosis." (PMID 39723390, 2024). "In addition, 4b and 4c exerted its anti-tumor effects by inducing cell apoptosis, upregulating the expression of cleaved-caspase 3 and cleaved-PARP and downregulating the protein levels of Bcl-2." (PMID 38398589, 2024). "The tumor tissue protein was extracted, and Western blotting indicated that DMF treatment resulted in decreased Bcl-2 expression and increased Bax expression in tumor tissues, resulting in a lower Bcl-2/Bax ratio (all p < 0.01)." (PMID 39444606, 2024).